TPD52 (tumor protein D52)
Diseases named in the same sentence as TPD52 in open-access papers (continued):
Sharing a sentence is not in itself a finding about the gene and the disease.
tumor (continued). "Furthermore, we determined that the expression of MAL2 and TPD52 in tumor cells was an independent predictor of OS according to the multivariate Cox model analysis." (PMID 28562687, 2017). "In conclusions, our findings suggested that TPD52 is a potential tumor suppressor in HCC." (PMID 26575170, 2016). "TPD52 expression was significantly correlated with tumor-nodes-metastasis (TNM) stage." (PMID 26575170, 2016). "Correlation analysis showed that decreased TPD52 expression in HCC was significantly associated with TNM stage, suggesting that decreased TPD52 expression may facilitate tumor invasion and infiltration." (PMID 26575170, 2016). "In particular, this included genes involved in secretory pathways, lipid and sugar metabolism (such as, UGDH, SORD, GLUD1, ELOVL5, ASCL3, UAP1), but also genes implicated in tumor progression and metastasis with functions in cell survival, proliferation and adhesion (EHF, ELL2, TPD52, MAFB, SGK)." (PMID 21829708, 2011). "Indeed, the log‐rank test demonstrated that the overall survival for patients with low TPD52 expression in tumor tissues was significantly higher than those with high TPD52 expression (p = 0.0036), suggesting that TPD52 expression correlates with poor patient prognosis." (PMID 35666017, 2023). "However, knockdown of TPD52 reduced tumor volume, and inhibition of HIF showed a stronger effect." (PMID 34217360, 2021). "Similarly, comparable overall survival was noted for tumours with high visually-scored MAL2 levels relative to all others, whereas significantly improved overall survival was noted in patients with tumours with high TPD52 staining (log-rank test, p < 0.001, n = 124)." (PMID 20846453, 2010). "The hub node in PRAD and adjacent normal prostate tissues was shown in, RIMKLA, TPD52, and SEPTIN3 were highly expressed in PRAD, while other genes were low-expressed in tumor tissues in." (PMID 40341647, 2025). "Functional enrichment analysis of genes coexpressed with Xiantao-derived TPD52 and TPD52L2 revealed distinct tumor-related pathways." (PMID 40973691, 2025). "Moreover, exogenous ATF6 expression abrogated the tumor‐promoting effects of TPD52 depletion, whereas ATF6 knockdown in cells transfected with TPD52 largely regained its proliferative capacity, suggesting that TPD52 might function through activation of ATF6 and subsequent promotion of ER stress." (PMID 39401430, 2024). "Several studies have reported upregulation of TPD52 in all four major histological types of EOC, concluding that it is a potential early tumor marker for detection as well as a plausible therapeutic target." (PMID 39309198, 2024). "This study found that tumor protein D52 (TPD52) integrates ER stress by promoting S2P‐mediated cleavage of ATF6, thus inhibiting tumor progression." (PMID 39401430, 2024). "Inactivation of HDAC2 leads to elevated TPD52 acetylation, which impairs the interaction between TPD52 and HSPA8, resulting in impaired CMA function and tumor growth in vivo." (PMID 36171897, 2022). "We found that the expression of TPD52 is higher in advanced-stage and metastatic breast cancer while the expression of KLF3 and miR-124 is lower in advanced clinical stages of tumor in comparison to initial stages." (PMID 33490232, 2020). "In our further investigation of the regulatory mechanism of Star-PAP in tumor progression, we noticed that it was reported that Star-PAP knockdown dramatically increased Tumor protein D52 (TPD52) expression." (PMID 31649118, 2019). "Real-time quantitative PCR was performed on 33 paired clinical samples from patients with HCC (tumor tissues and matched adjacent non-tumor liver tissues) and HCC cell lines to determine their TPD52 mRNA levels." (PMID 26575170, 2016). "We selected 5 known tumor-related genes i.e., K-ras, c-MYC, DNMT1, Tpd52, CDKN1b for PCR confirmation." (PMID 22206623, 2011).
tumor (continued). "Using siRNA to downregulate TPD52 expression in MCF‐7 cells resulted in notable cell proliferation and migration reductions, supporting the hypothesis that TPD52 is integral to tumour aggressiveness." (PMID 39757112, 2025). "This suggests that TPD52 may contribute to an immunosuppressive TME, potentially aiding in immune escape and tumour progression." (PMID 39757112, 2025). "TPD52 and IGKV3, exclusively identified in R GBM saliva, could be additionally distinctive of tumor relapse." (PMID 39684695, 2024). "TPD52 is found to be a tumour marker in ovarian cancer and its expression is absent in benign tumours." (PMID 35577881, 2022). "The expression of TPD52 was found to be significantly higher in the lower tumor stage and non-metastatic groups of patients in comparison to its high expression in the advanced tumor stage and distant metastatic groups of patients." (PMID 35047407, 2021). "However, the synergistic effect of TPD52 knockdown and inhibition of HIF drastically reduced tumor cell viability at the center of the tumor." (PMID 34217360, 2021). "Finally, we examined the synergy of TPD52 knockdown and inhibition of HIF in vivo by employing tumor xenograft mice." (PMID 34217360, 2021). "TPD52 mRNA expression was significantly down-regulated in 28/33 (85%) tumor tissues as compared with the matched adjacent non-tumor tissues (P = 0.0002)." (PMID 26575170, 2016). "Immunohistochemical analysis also revealed decreased TPD52 expression in most HCC tumor tissues as compared with the corresponding non-tumor tissues." (PMID 26575170, 2016). "Tumor-marker genes (HMGA2, TPD52, and GPC5) were overexpressed in U3-C and U3-DT." (PMID 25978455, 2015). "Significantly downregulated genes in NHT tumours (DESeq comparison; Benjamini-Hochberg P <0.05) were typically androgen responsive (for example, TMPRSS2, KLK3, BMPR1B, TPD52) or steroidogenesis-related (for example, DHCR24, SCD), consistent with a reduction in androgen receptor activity." (PMID 25155515, 2014).
TPD52 also shares sentences with these, for which no sentence is quoted: breast (2 papers); Burkitt lymphoma (2); hemangioma (2); multiple myeloma (2); nasopharyngeal carcinoma (2); adenocarcinoma of the (1); amyotrophic lateral sclerosis (1); benign prostatic hyperplasia (1); blood cancer (1); childhood leukemia (1); endometrial cancer (1); endometrioid carcinomas (1); insulinomas (1); intraepithelial neoplasia (1); lymph node metastasis (1); mental retardation (1); metastatic prostate carcinoma (1); metastatic tumors (1); oligodendroglioma (1); ovarian clear cell cancer (1); papillary renal cell carcinoma (1); papilloma (1); prostate adenocarcinoma (1); prostate adenomas (1); renal carcinoma (1); reproductive system disease (1); retinal degeneration (1); serous ovarian carcinoma (1); skin cutaneous melanoma (1); skin tumors (1).
A further 2 diseases each share a sentence with TPD52 in 1 paper.